GDF15 (growth differentiation factor 15)
Diseases named in the same sentence as GDF15 in open-access papers (continued):
Sharing a sentence is not in itself a finding about the gene and the disease.
Insulin resistance (continued). "In addition, injection of GDF15-deficient BMDMs induced an increase in homeostasis model assessment of insulin resistance (HOMA-IR) in both the vehicle-treatment and clodronate-treatment groups." (PMID 29674655, 2018). "Insulin resistance and increased GDF-15 both are associated with endothelial dysfunction." (PMID 26273671, 2015). "Elevated GDF15 concentrations in T2D patients might be considered as an anti-diabetic feed-back mechanism due to restricting effects on food intake and subsequent beneficial impact on weight loss and insulin resistance." (PMID 36430499, 2022). "Typically, these populations exhibit visceral adiposity which induces insulin resistance and chronic low-grade inflammation, these mechanisms triggering GDF-15 expression." (PMID 41597417, 2026). "GDF15 is important in energy homeostasis, demonstrated by GDF15 knockout mice preferring high‐fat foods and developing insulin resistance compared to healthy mice." (PMID 40019842, 2025). "Indeed, GDF-15 has been suggested to be a biologically active protein with therapeutic potential in metabolic disorders, given that it could effectively improve cardiovascular risk factors such as oxidative stress, insulin resistance, and dyslipidemia." (PMID 40371061, 2025). "Overall, these findings suggest a link between GDF15 nuclear levels and the occurrence of insulin resistance." (PMID 39825925, 2025). "GDF-15, a stress-responsive cytokine, has emerged as a potential player in muscle atrophy and insulin resistance." (PMID 38044678, 2024). "Future research should focus on elucidating the precise molecular mechanisms by which MMP-9, IL-6, IL-1, and GDF-15 derived from macrophages exert their effects on muscle atrophy and insulin resistance." (PMID 38044678, 2024). "It is important to note that the effects of MMP-9, IL-6, IL-1, and GDF-15 on muscle atrophy and insulin resistance are complex and intertwined." (PMID 38044678, 2024). "In the present study, we studied the correlation between GDF-15 levels, insulin resistance, and endocrine changes characteristic of PCOS-related infertility, and the possible influence of mtDNA deletion." (PMID 39456699, 2024). "Some studies have correlated increased GDF-15 levels with increased IL-4 levels and insulin resistance." (PMID 39420932, 2024). "In this section, we compared different treatments for insulin resistance in relation to patients’ plasma GDF-15 levels." (PMID 39456699, 2024). "GDF-15 concentrations have been reported to positively correlate with age, BMI, W/H ratio, adiposity, glucose, degrees of insulin resistance, and CRP." (PMID 37436597, 2023). "Plasma levels of both FGF21 and GDF15 are known to be increased in obese humans and rodents as well as in other metabolic disease states such as insulin resistance, NAFLD and mitochondrial disease." (PMID 36064109, 2022). "Combined whole body deletion of FGF21 and GDF15 does not result in any additional weight gain in response to high fat feeding but it does result in significantly greater hepatic steatosis and insulin resistance than that seen in GDF15 single knockout mice." (PMID 36064109, 2022). "At study base-line, GDF15 serum concentrations positively correlated with HbA1c levels—a marker for long-term elevated systemic glucose levels and insulin resistance." (PMID 36430499, 2022). "Further, exercise-mediated changes in serum FGF21 and GDF15 correlated with changes in the homeostasis model of assessment of insulin resistance (HOMA-IR) and appendicular lean mass (ALM), respectively." (PMID 33668309, 2021). "For example, GDF15 is closely related to insulin resistance, hyperandrogenemia, and menstrual disorder in PCOS." (PMID 34113617, 2021). "It was also demonstrated that upregulation of oxidative metabolism in ATM by stimulation with recombinant growth differentiation factor 15 (GDF15) led to M2-like polarization, reversing adipose inflammation as well as insulin resistance in mice." (PMID 34504646, 2021).
Insulin resistance (continued). "Plasma GDF15 levels increase during metabolic stress‐mediated tissue inflammation, including in insulin resistance and type 2 diabetes." (PMID 32691494, 2020). "GDF15 expression is suppressed in M1-like macrophages, which promote adipose inflammation and insulin resistance." (PMID 29674655, 2018). "Consistently, adeno-associated virus-mediated overexpression of GDF15 or recombinant GDF15 treatments reduces the adiposity and improves insulin resistance and glucose intolerance in various metabolic disease models." (PMID 30687235, 2018). "In our point of view, excluding anemic subjects is important to better understand the relationship between hepcidin, GDF-15, and insulin resistance." (PMID 27642607, 2016). "XENDOS study reported that plasma GDF-15 levels are positively associated with HOMA-IR, an index of insulin resistance." (PMID 26273671, 2015). "More specifically, the use of muscle-specific Gdf15 knockout mice might help to decipher potential new intricated mechanisms involved in the development of skeletal muscle insulin resistance." (PMID 39825925, 2025). "Recently, the plasma levels of GDF-15 and the presence or absence of mtDNA deletions were analyzed for the first time as potential biomarkers of mitochondrial dysfunction underlying insulin resistance, polycystic ovary syndrome, and associated infertility." (PMID 41302170, 2025). "Given the proposed role of the SMAD3-PA-I pathway in insulin resistance, these data suggest that deciphering the mechanisms involved in regulation of nuclear GDF15 levels may evolve into a new strategy to prevent the development of insulin resistance and T2DM." (PMID 39825925, 2025). "In this study, the plasma levels of GDF-15 and the presence or absence of mtDNA deletions were first analyzed as potential biomarkers of mitochondrial dysfunction underlying insulin resistance, polycystic ovary syndrome, and their associated infertility." (PMID 39456699, 2024). "GDF-15 may induce systemic inflammation and alter energy metabolism, contributing to muscle insulin resistance." (PMID 38044678, 2024). "The increased GDF-15 plasma levels observed in our investigated cases might be related to the severity of insulin resistance." (PMID 39456699, 2024). "GDF15 may contribute, in part, to the improvement of insulin resistance in HFD‐fed mice by potentially elevating serum adiponectin levels." (PMID 39700016, 2024). "Following mitochondrial stress, GDF15 expression is elevated in skeletal muscle, supporting whole‐body metabolic homeostasis, improving insulin resistance and preventing DIO through the promotion of lipolysis and oxidative metabolism in the liver, muscle and WAT." (PMID 39700016, 2024). "It reduces liver glucose production, enhances insulin sensitivity in body tissues, decreases hyperinsulinemia by reducing insulin resistance and increases the secretion of growth/differentiation factor 15 (GDF15), which suppresses appetite and reduces caloric intake." (PMID 38665260, 2024). "As insulin has an inhibitory effect on GDF15 secretion, hepatic insulin resistance may augment secretion of GDF15." (PMID 36545337, 2022). "Interestingly, we also found that GDF15 protects against hepatic steatosis and insulin resistance in mice fed an HFD, which was in contrast to our finding of fewer hepatic lipid droplets in FGF21-deficient mice." (PMID 33718833, 2021). "Furthermore, administration of GDF15 to obese mice improves the oxidative function of adipose macrophages and reverses insulin resistance." (PMID 29674655, 2018). "Age, insulin resistance, and creatinine were independent predictors of GDF-15 in obese patients." (PMID 26273671, 2015). "Additionally, the decrease in hepatic levels of fetuin‐A and Gdf15, along with an increase in apelin, might reduce insulin resistance and further support improved glucose metabolism." (PMID 39721028, 2025).
Insulin resistance (continued). "Considering that pro-inflammatory cytokines are also key contributors to the development of insulin resistance, the compensative increase in GDF-15 levels in response to IL-6 elevation might counteract this phenomenon, with a potential impact on clinical outcomes." (PMID 40283592, 2025). "Therefore, detecting a link between GDF-15 and insulin resistance might indicate a state of metabolic disorder." (PMID 39781722, 2025). "Additionally, peripheral GDF15 resistance could occur in diabetic states, similar to insulin resistance." (PMID 40174478, 2025). "The analysis revealed a significant and positive association between plasma GDF-15 levels and HbA1c (r = 0.297, p < 0.001), fasting blood glucose (FBG) (r = 0.269, p < 0.001), fasting insulin (r = 0.127, p < 0.001), and the homeostatic model of insulin resistance (HOMA-IR) (r = 0.198, p < 0.001)." (PMID 40722664, 2025). "The increase in PAI-1 levels in the skeletal muscle of HFD-fed Gdf15−/− mice is accompanied by changes in its targets HGFα and STAT3-SOCS3, leading to the development of insulin resistance." (PMID 39825925, 2025). "This increase in GDF15 levels was required to promote resistance to DIO and insulin resistance, due to an increase in lipolysis in adipocytes and hepatocytes." (PMID 37818094, 2023). "In mouse models of mild mitochondrial stress, chronically elevated FGF21 and GDF15 provide resistance to DIO and insulin resistance and ameliorate diet-induced hepatic steatosis and glucose intolerance." (PMID 37818094, 2023). "Additionally, insulin resistance might play a role in the acute regulation of GDF15." (PMID 36235718, 2022). "Intriguingly, Gdf15−/− mice fed AMLN diet for 30 weeks also had increased fasting glucose/insulin levels and homeostatic model assessment of insulin resistance (HOMA-IR) index compared to control mice." (PMID 29717162, 2018). "Induction of Gdf15 in response to oxidative stress and inflammation was increased in individuals with abdominal obesity, cardiovascular disease (CVD), and insulin resistance." (PMID 27977712, 2016). "Importantly, simultaneous deletion of Fgf21 and Gdf15 in BAT significantly attenuated the resistance to DIO and insulin resistance in OPA1 BKO mice." (PMID 40897647, 2025). "Notably, combined Fgf21 and Gdf15 deletion in OPA1 BKO significantly blunted the resistance to DIO and insulin resistance observed in OPA1 BKO mice." (PMID 40897647, 2025). "Background and Objectives: In this study, the effects of an eight-week exercise and nutrition program on blood lipids, glucose, insulin, insulin resistance (HOMA-IR), leptin, ghrelin, irisin, malondialdehyde (MDA), and Growth Differentiation Factor 15 (GDF15) in overweight women were investigated." (PMID 39768899, 2024). "In conclusion GDF-15 could have an adverse effect on sarcopenia and decrease skeletal muscle mass by activating FOXO1 and SMAD3, however, its protecting role against insulin resistance could reverse the process of sarcopenia." (PMID 38409184, 2024). "•Deletion of GDF15 and FGF21 exacerbate insulin resistance in mice." (PMID 36064109, 2022). "GDF-15 was investigated also as a predictor of future insulin resistance and impaired glucose control in obese non-diabetic subjects." (PMID 27056183, 2016). "Furthermore, a positive correlation was found between plasma GDF-15 concentration and insulin resistance, which was independent of age and BMI." (PMID 39456699, 2024). "GDF15 levels correlated positively with parameters indicative of altered metabolism (dyslipidemia, insulin resistance, metabolic syndrome) and inflammation) but did not correlate with currently used indices of CVR (Framingham score, D:A:D score) when age-adjusted." (PMID 35160008, 2022). "ALT, alanine aminotransferase; AST, aspartate aminotransferase; FGF21, fibroblast growth factor 21; Gdf15, Growth and differentiation factor 15; HOMA-IR, Homeostatic Model Assessment for Insulin Resistance; NEFA, non-esterified fatty acids." (PMID 36722855, 2023).
Insulin resistance (continued). "GDF15 levels correlated with LDL cholesterol, PUFA, MUFA, FGF21, and insulin resistance, even after age adjustment, whereas they did not correlate with triglycerides, HDL cholesterol, or non-HDL cholesterol." (PMID 35160008, 2022). "The present findings strengthen the rationale to raise the concentrations of circulating GDF15 in early PCOS, for example by a SPIOMET-like intervention that attenuates ectopic adiposity, insulin resistance and low-grade inflammation, without necessarily lowering body weight." (PMID 33782413, 2021). "The present findings strengthen the rationale to raise the concentrations of circulating GDF15 in early PCOS, for example with a SPIOMET-like intervention that attenuates low-grade inflammation, insulin resistance and ectopic adiposity, without necessarily lowering body weight." (PMID 33782413, 2021). "According to the literature, GDF-15 levels are not affected by GLP-1 receptor agonists; therefore, the increased GDF-15 plasma levels observed in our investigated cases might be related to the severity of insulin resistance." (PMID 39456699, 2024).
chronic kidney disease (80 papers, 2014 to 2026). Impairment of the renal function secondary to chronic kidney damage persisting for three or more months. "Higher GDF-15 concentrations have been linked to chronic kidney disease, microalbuminuria, and accelerated loss of kidney function in individuals suffering from diabetic nephropathy." (PMID 40722837, 2025). "Higher levels of GDF-15 are associated with an increased risk of chronic kidney disease, cardiovascular diseases, and pulmonary conditions like pulmonary hypertension and pulmonary fibrosis." (PMID 40149646, 2025). "In research conducted across two separate cohorts, it was found that elevated levels of GDF-15 were linked to more than a two-fold increase in the risk of eGFR decline in patients with chronic kidney disease (CKD)." (PMID 39781722, 2025). "While GDF15 has tissue-protective properties, as shown in acute kidney injury and chronic kidney disease, it promoted vascular injury and GDF15 deficiency protected against brachiocephalic trunk lumen stenosis after a cholesterol-enriched diet in ApoE−/− mice." (PMID 38732029, 2024). "Higher serum GDF-15 was associated with diabetic kidney disease and occurrence of incident chronic kidney disease." (PMID 34441955, 2021). "GDF-15 has been suggested as an independent risk factor of mortality in adults with end stage renal disease (ESRD) and for progression of kidney disease." (PMID 32089755, 2020). "Growth differentiation factor-15 (GDF15) is associated with inflammatory conditions, chronic kidney disease, cardiovascular disease and mortality." (PMID 32375259, 2020). "The aim of our study was to evaluate plasma and urinary levels of GDF-15 after pediatric renal transplantation (Rtx) and in children with chronic kidney disease (CKD) and its associations to cardiovascular risk factors." (PMID 32089755, 2020). "From both cohorts, circulating GDF15 associated with a 30% decline in eGFR or progression to end stage renal disease (ESRD)." (PMID 30542297, 2018). "Studies have found that cytokines involved in chronic inflammation, termed “inflammaging”, or senescent-associated secretory proteins such as IL-6 and GDF-15, have been implicated with decreased survival in normal aging, disease states like end stage renal disease, and in KTx recipients." (PMID 40612959, 2025). "Studies have similarly shown that measurements of circulating GDF-15 could be used to assess the prognosis and progression of chronic kidney disease, and that GDF-15 has been associated with the prediction of development of micro- and macroalbuminuria in T2D." (PMID 39000435, 2024). "Some studies have been conducted on specific patient groups, such as patients on hemodialysis or those with chronic kidney disease, where underlying diseases could affect the GDF-15 levels." (PMID 38672113, 2024). "Furthermore, high GDF15 levels have been observed in patients with old age and chronic kidney disease, and are closely linked to nutritional status." (PMID 39050134, 2024). "Several human and animal studies reported the association of GDF-15 with chronic kidney disease." (PMID 34441955, 2021). "Regarding nephrology, increased GDF-15 levels have been associated with higher risk of incident chronic kidney disease and more rapid decline in kidney function in different renal disorders, including diabetic nephropathy, IgA nephropathy, and primary membranous nephropathy." (PMID 33419237, 2020). "In our human study, GDF15 is also negatively associated with the glomerular filtration rate, which might be link to conspicuously frequent incidence of chronic kidney disease in patients with LD." (PMID 33003626, 2020). "It has been reported that the GDF15 level is significantly correlated with increased risk of chronic kidney disease (CKD) progression and higher mortality risk in CKD patients with hemodialysis treatment." (PMID 40673270, 2025).